INS (insulin)
Diseases named in the same sentence as INS in open-access papers (continued):
Sharing a sentence is not in itself a finding about the gene and the disease.
diabetes (continued). "Of the 36 who were diagnosed with manifest diabetes 14 were treated with metformin and two with insulin and metformin." (PMID 34078945, 2021). "Novel gastrointestinal surgeries that target diabetes, such as duodenal-jejunal bypass and ileal interposition, provide helpful clues to the mechanism of restored insulin sensitivity following bariatric surgery." (PMID 34513959, 2021). "Other groups have also investigated the role of RyR2 in insulin secretion patterns in diabetes mellitus." (PMID 34725342, 2021). "Although insulin therapy is often indicated in poorly controlled Type 2 diabetes mellitus (T2DM), this condition is more often managed with diet plus an array of medications that augment remaining endogenous insulin production and function." (PMID 34093449, 2021). "Mushroom terpenoids act as inhibitors of α-glucosidase and as insulin sensitizers through activation of PPARγ in order to reduce hyperglycemia in animal models of diabetes." (PMID 33467194, 2021). "For unannounced meals in a full closed loop system, and with faster insulin pharmacokinetics inherent to pigs, time‐in‐range was greater with open‐source algorithm AndroidAPS than Loop in pigs with diabetes." (PMID 33931977, 2021). "Compared with patients in the non-FoH group, patients in the FoH group showed a longer duration of diabetes (p = 0.029) and duration of insulin use (p < 0.001) and had more hypoglycemic episodes in the past year (p < 0.001)." (PMID 34744863, 2021). "Insulin injection technique re-education helps to facilitate improvement in glycaemic control by improving diabetes patient’s medication adherence, insulin injection technique and injection site inspection as well as perception towards insulin therapy." (PMID 34400860, 2021). "The elucidation of the incretin-insulin pathway prompted the development of DPP-4 inhibitors to prolong the circulating half-life of endogenous incretins to achieve glycemic control in diabetes patients, with a focus on drugs that can be taken orally." (PMID 34205264, 2021). "Although diabetes is characterized as a disorder of insulin resistance, a majority of the pharmaceutical treatments for this disease promote increases in insulin levels to achieve better glycemic control." (PMID 33531076, 2021). "The role of PCPs (and Certified Diabetes Educators) is to educate patients on insulin administration and titration and make sure they know when to get in touch with the provider, based on predefined glucose readings." (PMID 34165382, 2021). "Recent studies have reported that probiotics improve the symptoms of diabetes by regulating the intestinal microbiota composition, increasing insulin sensitivity, and mitigating autoimmune responses." (PMID 34213618, 2021). "Considering that the patient had diabetes mellitus, blood sugar levels remained normal upon treatment with insulin." (PMID 33438838, 2021). "The discovery of insulin in the 1920s transformed the lives of insulin-dependent people with diabetes." (PMID 33454830, 2021). "In contrast, LMO showed the most severe central obesity due to the severe hepatic insulin resistance, decompensated insulin secretion, and resultant poor metabolism (diabetes, dyslipidemia, and carotid lipid deposition)." (PMID 34335479, 2021). "By contrast, the International Diabetes Federation (IDF) guideline suggests that SMBG should be considered at the time of diagnosis for non-insulin-treated patients with T2DM as a part of their education to facilitate timely treatment." (PMID 33441946, 2021). "In 2018, 7.5% of individuals with diabetes were on insulin, and this number is expected to increase in the coming years." (PMID 34458301, 2021). "17.1% of women compared to 26.0% of men reported having their blood sugar tested, and women were less likely to take insulin for diabetes than men (AOR 0.53(95%) (0.23–1.22)." (PMID 34294059, 2021).
diabetes (continued). "Stress also impairs insulin sensitivity, while promotes metabolic syndrome and diabetes by altering the hypothalamic-pituitary-adrenal axis (via increased glucocorticoid and other stress hormones)." (PMID 33732985, 2021). "Both parents and children reported closed-loop insulin delivery improving their quality of life and reducing diabetes management burden." (PMID 33996702, 2021). "Diabetes mellitus (DM), a group of chronic metabolic disorders, is chiefly characterized by a persistently elevated blood glucose level due to deficiency and/or responsiveness of insulin." (PMID 34071497, 2021). "This is of importance as it can be used in the managements of diabetes through modulation of different targets (insulin, glycosylate insulin receptors, and glucose transporters)." (PMID 34760231, 2021). "Diabetes mellitus is a serious disease, characterized by abnormally elevated blood glucose levels due to a defect in insulin production or a reduction in insulin sensitivity and function." (PMID 34578651, 2021). "These molecules have been reported to help improve the glucose metabolism, endothelial dysfunction, and insulin function in diabetes." (PMID 34299638, 2021). "miR-34a regulates diabetes-related protein cascades in the insulin signaling pathway, glucose metabolism, and cell proliferation through Akt, phosphatase 1 nuclear targeting subunit (PNUTS), and SIRT1 expression." (PMID 35052597, 2021). "Further tests revealed the presence of low insulin secretion, which suggests that β cell functional defects due to DCAF17 gene mutation are among possible mechanisms for the development of diabetes in WSS." (PMID 35002959, 2021). "Adiponectin levels remained significantly lower in those with COVID‐19 after adjustment for age, sex, BMI, pre‐existing diabetes mellitus, enteral nutrition, glucocorticoid therapy, total insulin, APACHE II score, and SOFA score." (PMID 33904656, 2021). "To confirm the effectiveness of this diabetes model, we tested the blood glucose, body weight, and serum insulin levels at the end of the experiment." (PMID 34621323, 2021). "The discovery of insulin 100 years ago, led to a revolution in clinical medicine, as it allowed an effective treatment for diabetes." (PMID 33868177, 2021). "The current study aims to explore if a family history of diabetes can influence the efficiency of lifestyle intervention on insulin secretion and study the insulin resistance in Chinese men and women with metabolic syndrome in a cohort with a 2-year follow-up." (PMID 33490287, 2021). "The LDLT and HDLT significantly increased insulin levels compared to diabetes group in the present study." (PMID 33641315, 2021). "This study demonstrates the critical role of insulin signaling in diabetes-induced mechanical nociceptive hypersensitivity." (PMID 34549177, 2021). "Progression to diabetes is determined by the ability of the pancreatic β-cell to increase insulin production to adapt to increased insulin demand." (PMID 34531828, 2021). "Insulin secretagogues, which stimulate insulin secretion, and thiazolidinediones (TZD), which reduce the insulin resistance in adipocytes, liver and muscles, are other treatment options used for managing diabetes." (PMID 34445765, 2021). "It is mainly caused by eitherinsulin deficiency due to the destruction of insulin-producing beta cells of the pancreas(Fig Type 1 diabetes), or insensitivity of cells to insulin (Type 2 diabetes)." (PMID 34155870, 2021). "A higher BMI, reduced insulin secretion and action, a family history of diabetes, blood pressure, smoking status, and pregnancy status are considered common risk factors for type 2 diabetes." (PMID 34299797, 2021). "A systematic review of 78 publications reported that none of the methods identified are perfect as a measure of the quality of insulin adherence in patients with diabetes." (PMID 35002492, 2021).
diabetes (continued). "Diabetes is a disease state characterized by abnormal blood glucose concentration involving dysfunction of the pancreatic hormone insulin, produced by beta cells in the islets of Langerhans." (PMID 34368082, 2021). "Diabetes mellitus (DM) characterized by a defect of insulin secretion or insulin resistance is a chronic debilitating disorder." (PMID 34737903, 2021). "Postoperatively, 17 (94%) patients were diabetic, 14 requiring insulin, while three managed with oral anti-hyperglycemic medications (p = 0.041 compared to diabetes pre-operatively)." (PMID 34169341, 2021). "Diabetes is a serious, chronic endocrine disease that occurs when the blood glucose level is elevated due to insufficient insulin secretion and low sensitivity of target organs or cells to insulin." (PMID 33967955, 2021). "In diabetes, glycemic control is achieved by administration of antidiabetic medications that reverse the effects of its pathophysiological damaged insulin signaling." (PMID 34444990, 2021). "Most participants had been living with diabetes for more than 6 years (76.3%), used insulin pens for at least one year (71.2%), and injected insulin at least twice a day (87.5%)." (PMID 34497858, 2021). "Currently, there are limited data on the use of CGRP inhibitor mAbs in overweight or obese persons, patients with diabetes or subpopulations with metabolic abnormalities that include impaired glucose handling and insulin insensitivity." (PMID 33855218, 2021). "In several European countries, “expert patients” with diabetes who teach their peers to use insulin pumps usually have optimal glucose control, and are a powerful aid for endocrinologists to help enhance the use of medications by other patients." (PMID 34414588, 2021). "When insulin was introduced to the scientific world of diabetes in 1922, it immediately became clear that it was one of medicine’s most significant breakthroughs." (PMID 34572493, 2021). "Diabetes mellitus is a complex metabolic disorder characterized by hyperglycemia that results from defects in insulin secretion, insulin action, or both." (PMID 34388219, 2021). "Diabetes technologies fall into two major categories: devices for glycaemic self-monitoring and insulin delivery systems." (PMID 34184589, 2021). "In both types of diabetes, exogenous insulin is used to lower glucose therapeutically but due to the limitations of current insulin delivery, insulin replacement is unphysiological." (PMID 34814734, 2021). "Since physicians are the conduit between insulin suppliers and patients with diabetes, it is vital to understand the dynamics of insulin prescribing within a national sample of physicians." (PMID 34061852, 2021). "Diabetes mellitus is a chronic metabolic disease that is characterised by chronic impaired blood glucose levels and hyperglycaemia as a result of compromised insulin secretion or impaired insulin action." (PMID 34759766, 2021). "One of the hypoglycemic events in each treatment group occurred during insulin treatment after 33 and 51 months in individuals whose diabetes rapidly progressed." (PMID 34130731, 2021). "Resistin is known as a hormone that potentially links obesity to diabetes through resisting insulin action." (PMID 35602208, 2021). "On a much smaller scale, this was also demonstrated in our study, as in patients with established disease, on intensive insulin treatment, sCAM and E-selectin concentrations decreased compared to children with newly diagnosed diabetes." (PMID 34603200, 2021). "They assessed individual indices such as BMI, waist circumference, FBS, triglycerides, insulin, Homa‐IR index, total glucose metabolism and TyG‐index to recognize IR in subjects who were healthy, obese, had prediabetes and diabetes." (PMID 33532603, 2021). "Diabetes is a metabolic disease that is characterized by an increase in blood glucose, or hyperglycemia, often due to dysfunctional insulin production or signaling." (PMID 34564296, 2021).
diabetes (continued). "Insulin pens were first introduced in 1987 and partially address quality of life and diabetes outcome-related barriers to insulin delivery with vial and syringe (including convenience, dosage, pain, and hypoglycemia)." (PMID 37745178, 2021). "Wilkin argued that the primary factor differentiating diabetes type is the tempo of progression to overt clinical disease, driven by the interplay between β-cell reserve and insulin sensitivity." (PMID 33828529, 2021). "Nevertheless, labor and cost reductions are considered advantageous in developed countries, especially when patients treated with IV insulin are required to be admitted to an ICU or a specialized diabetes care unit." (PMID 33945208, 2021). "Patients with T1D, who constitute the minority of patients with diabetes, frequently adopt personalized insulin delivery schedules and monitoring systems." (PMID 33769945, 2021). "TNF-α can lead to the development of diabetes by affecting insulin action, and levels of inflammatory cytokines and markers are reported to be increased in diabetes patients." (PMID 34867341, 2021). "In Pakistan in recent years, there has also been an increase in insulin utilisation reflecting increased prevalence rates for diabetes mellitus." (PMID 34249838, 2021). "Most patients took oral medications for diabetes (48.3%) and 28.5% took both insulin and oral medications." (PMID 34745773, 2021). "Insulin resistance (IR) is a physiological condition related to type 2 diabetes mellitus (T2DM) and obesity, which is also associated with high blood insulin and glucose." (PMID 34272768, 2021). "Different treatments are currently used to manage diabetes, such as insulin, dietetic therapies, and pharmacotherapy, which exert antidiabetic effects by different mechanisms." (PMID 33802826, 2021). "Additionally, a meta-analysis of 14 cross-sectional studies reported that female sex, insulin use, diabetes complications, low educational level, physical inactivity, living alone, and unemployment were significant risk factors for depressive symptoms in people with diabetes." (PMID 34442186, 2021). "Nowadays, the use of closed-loop systems with continuous glucose monitors and insulin pump therapy with fast or ultra-fast insulin provide a more flexible way to control diabetes." (PMID 34372462, 2021). "Meanwhile, the mRNA levels and activity of these HDACs displayed an inverse correlation with inflammatory markers, obesity indices, and insulin levels, indicating that these HDACs have adverse effects on the development of obesity and diabetes mellitus." (PMID 34301918, 2021). "This research is of great significance to human health, because β cells are the only cells that produce insulin, and insulin is responsible for regulating blood sugar metabolism, which is closely relative to diabetes." (PMID 34604109, 2021). "Type 2 diabetes mellitus (T2DM) is a multifactorial disease that associates insulin resistance and decreased insulin secretion." (PMID 33435513, 2021). "Although, TCF7L2 is considered to play function in insulin secretions from pancreas but the exact mechanism for the gene involvement in diabetes development is unclear." (PMID 34394276, 2021). "This study is relevant within the Brazilian context as it identified a group of patients with diabetes receiving only insulin analogues." (PMID 33905630, 2021). "Sodium-glucose cotransporter 2 (SGLT2) inhibitors, which block glucose reabsorption in the kidneys, represent a novel class of non-insulin glucose-lowering medication used in the pharmacological therapy of type 2 diabetes mellitus (T2DM)." (PMID 34335470, 2021). "Recent advances in diabetes technology have led to the development of closed-loop insulin delivery systems for the management of type 1 diabetes." (PMID 33996702, 2021). "For example, bariatric surgery improved diabetes mellitus through the improvement of insulin sensitivity." (PMID 34684569, 2021).
diabetes (continued). "Different studies suggested promising results of KD to help patients to lose weight, to reduce insulin requirements in diabetes, to supplement cancer protocols, to treat neurological conditions and to optimize control of metabolic and cardiovascular diseases." (PMID 34970568, 2021). "At study inclusion, 50% of the patients in our cohort were being treated with insulin, after a median duration of diabetes of 9.9 years (4.3 to 12.3 years)." (PMID 34830599, 2021). "Fasting blood glucose testing was even less common in French Guiana’s treated diabetes population: 45.8% (n = 2937) of insulin-treated patients and 44% of non-insulin-treated patients (n = 1613) had at least 2 blood glucose tests in 2019." (PMID 34917037, 2021). "Among 511 participants who were taking oral hypoglycemic agents or using insulin to treat diabetes, 311 were using metformin." (PMID 34966358, 2021). "Distinctive pathophysiological profiles in pre-diabetes phenotypes have been described based on insulin secretion, insulin sensitivity, and beta-cell dysfunction assessed by IFG, IGT, and Hb1Ac measurements." (PMID 34790686, 2021). "Use of insulin is also influenced by the patient’s socioeconomic status, poor knowledge of diabetes, traditional beliefs, use of traditional medicine and misperception of insulin as a ‘last resort’ therapy." (PMID 33483763, 2021). "Adequate treatment adherence, defined as attending ≥2 visits where counselling, medications and/or insulin were received, was demonstrated by 45.4% (hypertension), 55.3% (diabetes), and 82.1% (both conditions) patients." (PMID 33777712, 2021). "In this study, we examined the effects of STZ-induced diabetes and insulin treatment on γ-BBH and OCTN2 expression in liver and kidney as well as on FC levels in plasma, urine, and tissues in diabetic rats." (PMID 34833964, 2021). "The rise in the number of diabetics worldwide would lead to the consequential increase in the demand for insulin." (PMID 34336550, 2021). "Diabetes, characterized by insufficient production or usage of insulin, has become a significant public health concern." (PMID 33802091, 2021). "Because of genetic abnormalities affecting β-cell mass and insulin production, East Asians have an increased chance of acquiring diabetes." (PMID 34822452, 2021). "Overall relations of cognitive function with various factors (such as age, insulin dose, HbA1c, metabolic syndrome, BMI, metformin usage and diabetes duration) in T2DM were analyzed." (PMID 34577866, 2021). "These various factors that impair diabetes care result in a low or decreased life-expectancy for people with type 1 diabetes and a gap in access to insulin for people with type 2 diabetes, which, in turn, can lead to excess morbidity and mortality." (PMID 33483763, 2021). "Distribution of podiatrist consultations according to the regions of the territory and according to the insulin therapy of patients with diabetes." (PMID 34917037, 2021). "LFS uses serum aspartate transaminase/alanine transaminase (AST/ALT) ratio, fasting serum aspartate transaminase (AST) level, fasting serum insulin level, presence of metabolic syndrome and diabetes mellitus to calculate the score." (PMID 34184611, 2021). "According to this classification, diabetes technology has 2 main categories: insulin administration and blood glucose monitoring." (PMID 34081010, 2021). "Type 1 diabetes mellitus usually presents itselft in early to mid childhood as a defect in insulin production through the autoimmune destruction of pancreatic beta-cells." (PMID 34556755, 2021). "Diabetes mellitus is a pandemic metabolic disorder that results from either the autoimmune destruction or the dysfunction of insulin-producing pancreatic beta cells." (PMID 33477961, 2021). "It is known that HOMA-IR is a validated index to evaluate the sensitivity to insulin while IGR is proposed to predict the appropriate choice of glucose-lowering drugs for managing diabetes." (PMID 34209137, 2021).